CD4 (CD4 molecule)
Diseases named in the same sentence as CD4 in open-access papers (continued):
Sharing a sentence is not in itself a finding about the gene and the disease.
tumor (continued). "These host CD4+ T cells are found to be adequate for optimal tumor protection mediated by NKG2D CAR-expressing T cells but are not necessary if CD4+ T cells are adoptively co-transferred." (PMID 40612946, 2025). "Flow cytometric assessment of the T cell activation marker programmed cell death protein 1 (PD-1), an important target of immune checkpoint inhibition, revealed that PD-1 expression in tumor-infiltrating CD8+ and CD4+ T cells was comparable between NSG, NSG-Quad, and MISTRG-6 mice." (PMID 40503011, 2025). "CCLs play a crucial role in modulating the tumor microenvironment, particularly by influencing immune cell infiltration, including B lymphocytes, Timer_Neutrophils, Timer_Macrophages, dendritic cells, CD8+ T cells, and CD4-positive cells." (PMID 39859340, 2025). "Chemokines often recruit pro-tumourigenic immune cells such as MDSCs, TAMs, TANs and regulatory T cells etc. to stimulate the growth and proliferation of tumour cells, while recruitment of CD4+ T cells, CD8+ T cells and NK cells inhibit tumour growth, invasion and metastasis." (PMID 40852716, 2025). "As N2-polarized TANs, they suppress CD4+ and CD8+ T cell activity through mechanisms such as myeloperoxidase (MPO) and Fas/FasL expression, while they also release immunosuppressive factors that promote tumor growth, metastasis, and immune evasion." (PMID 40647470, 2025). "Additionally, the IHC results indicated an increase in CD4, CD8, and IL-17 expression in the tumor area of the mice that received the KLH-PD-L1-SARS vaccine." (PMID 41455906, 2025). "Together, these data establish that expanded EC TIL products retain autologous tumor reactivity in an HLA-dependent manner, with both CD8+ and CD4+ subsets contributing to effector responses through distinct activation pathways (4-1BB vs. OX40) and potent Th1 cytokine production." (PMID 40806287, 2025). "In GBM, LSM2 expression exhibited a significant positive correlation with tumour purity (r = 0.301, p < 0.001) and neutrophil infiltration (r = 0.116, p < 0.05), and a weak negative correlation with CD4+ T cell infiltration (r = -0.115, p = 1.85e-02)." (PMID 40365337, 2025). "Unlike CD8+ T cells, CD4+ T cells have less clearly defined roles in tumour development, exerting anti-tumour effects through effector cytokines, cytotoxicity, and T cell help." (PMID 40351814, 2025). "There was no NK cell cluster present in the tumor infiltrating immune population, as analyzed by snRNAseq, and subclustering found predominantly CD4 T/Treg cells, with CD8 T cells constituting only 20-40% of infiltrating T cells." (PMID 40821787, 2025). "Pharmacodynamic analysis demonstrated a positive correlation between the angiogenic marker Ang-2 and tumour burden, with improvements in CD4 cell counts observed and no detrimental impact on ART drug levels or HIV viral load." (PMID 40108492, 2025). "CD4+ T cells are necessary for the proliferation and differentiation of CD8+ T cells, the generation of memory CD8+ T cells, and their infiltration into the tumor." (PMID 40650111, 2025). "The results revealed a significant increase in the frequency of ascitic TEM in CD4+ T cells but not in CD8+ T cells in Tnfrsf14KD‐ID8 tumor‐bearing mice." (PMID 40105652, 2025). "In our patient, the cells showed a CD4-/CD8+ and CD56-negative phenotype, indicating that the tumor cells were predominantly cytotoxic T-cells (CD8+ T-cells), which are involved in mediating immune responses and killing tumor cells." (PMID 40666527, 2025). "Moreover, the proportion of CD4+ and CD8+ subsets of CAR-T cells is a meaningful effect related with its anti-tumor efficacy." (PMID 41293181, 2025). "However, CD69+CD4+ T cells barely expressed CD103 compared with CD69+CD8+ T cells, and slightly lower frequencies of CD69+CD8+ T cells were observed in the tumor tissues than in liver tissues." (PMID 40361474, 2025).
tumor (continued). "The positive correlation between NTRK3 expression and dendritic cells, CD4+ T cells, and CD8+ T cells indicates that NTRK3 may be involved in modulating immune responses in the tumor microenvironment." (PMID 40142285, 2025). "CD4 T cells support CD8 T cell activation and memory formation by providing cytokines such as IL-2, enhancing dendritic cell function, and sustaining immune cell recruitment to the tumor microenvironment (TME)." (PMID 40076932, 2025). "This further suggests that CD4+ and CD8+ T cells contribute to tumor immune defense." (PMID 39958339, 2025). "Importantly, DCs phagocytose apoptotic tumor cells, process tumor antigens, present them via MHC‐I and MHC‐II molecules, migrate to regional lymph nodes, and activate naive CD4+ and CD8+ T cells to initiate an antitumor immune response." (PMID 41049266, 2025). "In addition, both CD4+ and CD8+ T cells from arginine- or citrulline-fed mice displayed enhanced function shown by an increase in IFNγ production in the tumor, with the biggest increase found in citrulline-treated groups." (PMID 40742298, 2025). "Neither abemaciclib nor RT combined with aPD-L1 increased CD4 + T cells, CD8 + T cells, or tumor-associated macrophages as effectively as the triple combination, as confirmed by IHC staining." (PMID 40836337, 2025). "Furthermore, tumor tissue analysis showed a 5.29-fold increase in CD8+ T cells and a 3.17-fold increase in CD4+ T cells in the THZO + US group compared to controls." (PMID 41402300, 2025). "Additionally, CD4+ and CD8+ T cells from tumor samples of eHCC patients exhibited higher PD-1 expression compared to their snTIL counterparts." (PMID 40547009, 2025). "In a specific dataset (GSE103322) containing 5,902 single cells derived from 18 patients with HINSCs, SUSD3 expression was found to be particularly evident in CD4+ T conventional cells (Tconv), cytotoxic T lymphocytes, and CD8+ T-exhausted (Tex) cells within the HINSC tumor microenvironment." (PMID 40191190, 2025). "The few CD4+ T cells recruited to tumours were mainly Tregs and as such, they did not substantially contribute to IFNγ production." (PMID 39746898, 2025). "Furthermore, we observed increased infiltration of CD3+, CD4+, CD8+ T cells, and NK cells into the tumor microenvironment, along with a decrease in overall macrophage density." (PMID 39979981, 2025). "Additionally, the activation status of CD4+ and CD8+ cells in tumor tissue was significantly enhanced." (PMID 41383334, 2025). "In the absence of vaccine therapy, the frequency of total CD4+ T cells infiltrating the tumor decreased over time." (PMID 40196575, 2025). "In contrast to the observed increase in inflammatory helper T cell subsets in the periphery of the CD4-Cre PRR cKO mice, the number of tumor-infiltrating CD4 and CD8 T cells was significantly lower, and the frequency of IFN-γ-producing cells was unchanged compared to that in control mice." (PMID 41451235, 2025). "This functional imbalance between CD4+ and CD8+ T cells may collaboratively contribute to tumor immune evasion." (PMID 41194936, 2025). "Similarly, neutralizing CD8+ or CD4+ T cells in orthotopic MOC2 mice abolished the therapeutic benefits of C‐P, i.e., the durability of tumor regression." (PMID 40936164, 2025). "Notably, the expression of the CD81 molecule on both tumor-infiltrating CD8+ and CD4+ T cells was significantly enhanced following GCP combination therapy, emphasizing the potential role of CD81 in T-cell reactivation." (PMID 41409288, 2025). "While neither macrophage/monocyte nor B-cell depletion impacted tumor responses to the triple combination, depletion of CD4 T cells and, to a lesser degree, CD8 T cells accelerated tumor relapse." (PMID 40299790, 2025). "Low TTC36 expression correlated with reduced infiltration of B cells, CD4+ T cells, dendritic cells, and neutrophils, suggesting TTC36 may function as a potential regulator of the tumor immune microenvironment." (PMID 41208883, 2025).
tumor (continued). "Further study showed that both viruses could induce CD8+ T cells to infiltrate into tumor tissues, but VVL-TD-RFP significantly increased the infiltration of CD4+ T and NK cells in the TME." (PMID 40350204, 2025). "Dendritic cells capture tumor antigens, instigating CD8+ or CD4+ T cell-mediated immune responses." (PMID 39781524, 2025). "Given the critical role of tumor microenvironment (TME) in oncogenesis, we performed subclustering analysis of T/NK cells, identifying four distinct subsets: natural killer (NK) cells, CD4 + T cells, CD8 + T cells, and regulatory T cells (Tregs)." (PMID 41187171, 2025). "In this analysis of CD4+ T cells, we noted, for example an enrichment of cluster 6 CD4+ T cells close to CK+ tumor cells within the tumors from PWOH, which was not noted in tumors from PWH." (PMID 40459946, 2025). "Analysis of the tumor microenvironment revealed a shift toward a pro-inflammatory state, characterized by an increased CD8+/CD4+ T-cell–to–macrophage/MDSC ratio, reduced intratumoral TGF-β levels, and enhanced proliferation and activation of CD4+ and CD8+ T cells." (PMID 41568361, 2025). "Increased ICOS-positive CD4+ and CD8+ T cells enriched in Icosl-KO tumor." (PMID 40708008, 2025). "There is a clear correlation between higher expression of LAG3 in TIL and closer proximity of T cells to tumor cells, where LAG3 predicts more CD4 + or CD8 + T cells clustered around the tumor, and immune activation within the TME prompts more effector T cells to exert tumor-killing effects." (PMID 40411616, 2025). "They secrete cytokines that promote T-cell depletion while simultaneously reducing the capacity of CD8+and CD4+T cells to eradicate tumor cells within the TME, contributing to tumor progression, immune evasion of neoplastic cells, and resistance to cancer immunotherapy." (PMID 40670983, 2025). "In addition to an exhausted or dysfunctional/tolerogenic phenotype of effector T cells in the GBM TIME, CD4+ TH are often skewed toward a TH2 phenotype, which is less effective in anti-tumor immunity compared to TH1." (PMID 40075663, 2025). "Furthermore, certain immune cells (e.g. CD4 T cells) within the TME are involved in immune surveillance by recognizing and destroying tumor cells." (PMID 41185082, 2025). "In addition, ST2+ Tregs from tumor tissue inhibit CD4+ and CD25 T cell proliferation and IFN-γ production, promoting tumor progression." (PMID 39925809, 2025). "An in vitro killing assay was established using tdTomato+CD4+ T cells, characteristic of effector CD4+ T-cell population, isolated from GSC005 tumor of GzmBCreRosa26tdtomato mice post-treatment, as effector cells, and in vitro-cultured GSC005 tumor cells as target cells." (PMID 39885128, 2025). "Furthermore, the tumor microenvironment was completely reshaped toward anti-tumor inflammatory cells, as illustrated by changes in the CD8 to CD4 ratio and IFNγ-producing CD8+ T cells to T-regs ratio in the huCC49-IL-2-treated tumors and lymphoid organs." (PMID 40361381, 2025). "Taken together, the long-term follow-up of the AMPLIFY-201 phase 1 study provides evidence that ELI-002 2P induces potent, polyfunctional CD4+ and CD8+ T cell immunity to mKRAS alongside frequent antigen spreading that may delay tumor recurrence." (PMID 40790272, 2025). "Anlotinib has been identified as facilitating the normalization of tumor vasculature, potentially through the activation of CD4+ T cells, which remodels the suppressive TME into a stimulatory one, thereby significantly curbing tumor growth and preventing systemic immunosuppression." (PMID 40718780, 2025). "Accordingly, the frequencies of CD69 and CD103 expressing cells were dramatically higher in both CD4+ and CD8+ T cells’ population from tumor samples than from PB, both in the case of W‐L GBM and in the case of all the three layers of 5‐ALA resected GBM, compared with PB." (PMID 40498413, 2025).
tumor (continued). "However, despite demonstrating similar CD4+ mediated GVHD, the allorecipients of SDHA-KO and WT cells still demonstrated similar tumor-related mortality, demonstrating similar magnitude of preservation of CD8+ T cell–mediated GVT effects after allo-HCT." (PMID 41392980, 2025). "Conversely, TNRTs CD4+ TGF-β1+ T cells and CD8+ Temra cells exhibited significant expansion in the ICB-NRs, indicating a parallel in cellular dynamics between peripheral blood and tumor samples." (PMID 40054456, 2025). "Additionally, the involvement of resting CD4 memory T cells suggests a potential dysregulation of adaptive immunity in MYCN‐amplified NB, indicating a mechanism by which the tumor evades immune surveillance." (PMID 40600620, 2025). "The correlation of MLR between blood and tumours (median of macrophage markers expression/median of CD4+ T markers expression) was also not significant (Kendall’s coefficient = −0.17, p-value = 0.126)." (PMID 40858716, 2025). "CD4+ Th1 cells secrete IFN-γ and TNF-α to trigger CD8+ T and NK cells to eliminate tumor cells." (PMID 39782693, 2025). "The pseudotime development of CD4+ CXCL13+ Tfh cells in the blood might indicate that the development of CD4+ CXCL13+ Tfh cells might be residential, i.e., occurs locally in the tumor compartment." (PMID 40054456, 2025). "These vesicles could activate CD4+ and CD8+ T cells, alleviate the immunosuppressive effect of the tumor microenvironment and enhance the intensity of anti-tumor immune responses." (PMID 40717972, 2025). "Additionally, within the tumor microenvironment, we observed a correlation between FAM111B and CD4+ T cells in the OV tissue microarrays; however, our analysis did not distinguish between specific subtypes, such as Th1 and Th2 cells." (PMID 40243892, 2025). "The proportions of CD4 memory T cells, CD8 T cells, activated B cells, Memory B cells, and Macro_Mono in the TLSHigh group were significantly increased, while the proportions of epithelial tumor cells and CAF were notably decreased." (PMID 40959083, 2025). "In addition, CTLA4 was highly expressed in the CD4 + FOXP3 T03 subcluster, which only accounted for 16% of cells in tumours." (PMID 39548315, 2025). "CD4+ Tconv in the blood contained the highest proportion of Tn (31.2% in blood vs. 8.2% in MPE vs. 5.9% in tumor) and the highest expression of the memory marker CD127 (93.1% in blood vs. 72.0% in MPE vs. 73.9% in tumor)." (PMID 41415427, 2025). "An upward trend in CD4 T cells within the non-metastatic group suggests a potential anti-tumor effect mediated by CD4 T cells." (PMID 40575173, 2025). "We hypothesize that Inhibiting HO-1 can reverse these effects, enhancing the infiltration and activity of CD4+ and CD8+ T cells within the tumor, thereby supporting a more robust and sustained immune response against cancer." (PMID 40037158, 2025). "However, higher infiltration of CD4_1, CD4_4, CD4_6, and CD8_1 cells was closely associated with better prognosis in the HNSC cohort of The Cancer Genome Atlas (TCGA), indicating that CD4+ and CD8+ T cells possessed anti-tumor properties." (PMID 40360503, 2025). "The interface scores closely matched the whole‐tumour results: MP2 maintained epithelial cells and plasma cells; MP3 enriched CD4 T cells, endothelial cells and macrophages; MP4 exhibiting elevated CD8 T cells, mast cells, monocytes and NK cells; and MP7 accumulated fibroblast." (PMID 40292733, 2025). "Senescent cell populations, particularly CD8+ and CD4+ T-cells, can secrete a variety of SASP factors (pro-inflammatory cytokines, chemokines and growth factors), that can remodel the immune landscape and influence the TME towards tumour progression." (PMID 41372921, 2025). "Furthermore, in an orthotopic CCA model, Aurkine 16 significantly reduced tumor volumes compared to controls, along with an increase in p-H2AX+ cells and enhanced infiltration of CD8+ and CD4+ T cells into tumors." (PMID 40324694, 2025).
tumor (continued). "Malignant CD4 cells from tumor-stage lesions did not have significantly different CD5 expression compared to healthy controls (log2 fold change of −0.24, adjusted p-value > 0.05)." (PMID 41226451, 2025). "Furthermore, 4-1BB signaling also stimulated CD4+ effector T cells to expand and produce proinflammatory cytokines, such as IFN-γ and TNF-α, providing a proinflammatory environment that favored tumor rejection." (PMID 40067370, 2025). "The spleen samples showed increased infiltration of CD4+ and CD8+ T cells as well as M1 phenotype macrophages, suggesting a systemic immune activation despite the limited local infiltration observed within the tumor." (PMID 40548883, 2025). "The metastatic niche presentation of SFB epitopes activates tumor-infiltrating Th17 cells strongly, which then initiate a complex anti-tumor cytokine cascade through increased IL-17A and IFN-γ production by CD4+ T cells and CD8+ T cells, and natural killer cells." (PMID 41441899, 2025). "Recently, we compared zirconium-89 (89Zr)–labeled human and mouse CD4-specific minibodies in different syngeneic tumor models and successfully identified responders to combined αPD-L1/αLAG-3 ICI therapy in an MC38 tumor mouse model based on the whole-tumor PET uptake." (PMID 40561008, 2025). "Tumor margin infiltration was observed less frequently in CD4-positive patients, being more common in CD4-negative cases." (PMID 40362599, 2025). "Immune responses included sustained mKRAS-specific CD4+ and CD8+ T cell subsets exhibiting favorable effector cytokine function, cytotoxic markers and memory phenotype, as well as antigen spreading to personalized tumor antigens beyond the immunizing antigens." (PMID 40790272, 2025). "There was a negative correlation between the ratio of IFN-γ in CD4 + T cells in baseline tissues and the average CD4 + T cells number around the tumor (Spearman ρ = −0.421, p = 0.046), but no trend was observed within CD8 + T cell subsets." (PMID 40411616, 2025). "The number of T cells within the tumor area had little effect on the overall survival time, and not CD4 + or CD8 + cells, but the density of LAG3 + T cells showed a strong correlation with prognosis (43.0 vs 9.1 months, p < 0.001)." (PMID 40411616, 2025). "In contrast, nonresponsive tumors showed a ubiquitously reduced 64Cu-CD4-Nb1 uptake (T cell–deserted) or signal accumulation predominantly at the tumor margin (T cell–excluded)." (PMID 40561008, 2025). "We observed infiltration of CD4+ and CD8+ T cells, increased CD8+ T cell and NK cell activation, and exclusion of pro-tumor M2 macrophages and mononuclear myeloid-derived suppressor cells (M-MDSCs) in tumors treated with therapeutic antibody as analyzed by flow cytometry." (PMID 40391157, 2025). "Importantly, the pharmacological inhibition of PHF8 with daminozide synergized with anti-PD1 antibody in vivo, leading to increased tumor infiltration with CD4+ and CD8+ T cells, and slower CRC tumor growth." (PMID 40940894, 2025). "The antigen specificity of the expanded CD4+ T cells post-M002 treatment is unclear, as these cells could be reactive to HSV antigen or tumor antigen." (PMID 39885128, 2025). "These CD4+ T cells facilitate the maturation of DCs through interactions involving CD40-CD40L and MHC II/epitope-TCR, which allows for the cross-presentation of tumor antigens to CD8+ T cells." (PMID 40698086, 2025). "Similarly, other research has shown that both circulating CD4+ and CD8+ T cells were reduced, and tumor growth increased in mice treated with steroids alone or in combination with anti–PD‐1 therapy, ultimately diminishing the therapeutic efficacy." (PMID 40641448, 2025). "Additionally, CD4+ T helper 2 (TH2) cells, induced by IL-10 from tumor-infiltrating MDSCs, can inhibit CTL activity." (PMID 41041128, 2025). "In contrast, Foxp3 protein depletion caused a preferential expansion of effector CD4 and CD8 T cells in the tumor-draining, but not the non-draining lymph node." (PMID 40478934, 2025).